PCNA (proliferating cell nuclear antigen)
Diseases named in the same sentence as PCNA in open-access papers (continued):
Sharing a sentence is not in itself a finding about the gene and the disease.
tumor (continued). "In line with above studies, we proofed that the changes of ZNF750 expression led to the changes of tumor growth, which manifested by decreased tumor volume and tumor weight, reduced Ki67 and PCNA expression in oe-ZNF750 groups, but all of these was increased in sh-ZNF750 groups." (PMID 35003347, 2021). "Furthermore, in nude mice, ADFP promoted tumour formation with high levels of p‐Akt/Akt, Ki67 and proliferating cell nuclear antigen (PCNA)." (PMID 33249703, 2021). "Thus, we report a novel mechanism that constitutes the basis for tumor growth by which the γ-tubulin meshwork maintains indefinite proliferation by acting as an opportune scaffold for the transport of PCNA from the cytosol to the chromatin." (PMID 34158617, 2021). "Moreover, the xenografts from miR-30e-overexpressing Kyse30 cells showed lower expression levels of PCNA by IHC staining compared to control, demonstrating that forced expression of miR-30e inhibited tumor cell proliferation." (PMID 34727092, 2021). "Next, to further elucidate the mechanism by which FBXO43 affect cell functions in BC, we conducted a Co-IP assay and found that FBXO43 could regulate tumor growth by interacting with PCNA." (PMID 34645483, 2021). "Tumour proliferation and apoptosis were examined by Ki-67, PCNA and TUNEL staining." (PMID 34214017, 2021). "Interestingly, the markers studied (IRS-4, PCNA, Ki-67, or pH3) increased significantly in the group G2 with respect to G1 group, which suggests a relation with tumor grade." (PMID 34071030, 2021). "Consistent with our hypothesis, we found a significant positive correlation between TUBG1 and PCNA expression in all the datasets we examined (33 tumor subtypes, N = 9,664)." (PMID 34158617, 2021). "The vehicle group showed fewer PCNA+ cells in the mucosal areas of non-tumor regions." (PMID 33808480, 2021). "The functional effect of other inhibitors on tumor development and whether they target the regulatory sites of PCNA by SETD8 requires further identification." (PMID 34671219, 2021). "(K) The density of proliferating cell nuclear antigen (PCNA)-positive cells in tumor tissue." (PMID 34528509, 2021). "PCNA is a cell nuclear protein whose expression is correlated with DNA replication, regulating the transition from G1 phase to S phase, and is connected with the proliferation of tumor cells." (PMID 34237060, 2021). "In addition, our observations reveal a mechanism for targeting the nuclear activity of PCNA that involves interfering with the transport-assisting function of the γ-tubulin meshwork in tumor cells." (PMID 34158617, 2021). "Furthermore, the results of Western blotting of the tumor showed that PCNA, cyclin D, and vimentin protein were substantially overexpressed in the scramble control group in comparison with the MICAL2-knockdown group." (PMID 34868922, 2021). "Moreover, the expressions of ki67 and PCNA were markedly reduced in the tumor tissue of PC-bearing nude mice." (PMID 34899908, 2021). "Treating with Sal and Doc could induce tumor apoptosis and inhibit tumor proliferation, evidenced by significant increase in the expression of Caspase3 and decrease in the expression of Ki-67 and PCNA." (PMID 33657950, 2021). "Results indicated that KI67 and PCNA was decreased in the tumor tissues with low FUT11 expression." (PMID 34221996, 2021). "Furthermore, the protein levels of Wnt7B and PCNA were declined, whereas the ratio of cleaved-caspase 3/total-caspase 3 was elevated in tumor tissues from the sh-irc_0082375 group." (PMID 34868669, 2021). "Furthermore, the suppressed tumor growth in groups receiving extract showed diminished fluorescent mitotic index proliferating cell nuclear antigen (PCNA)." (PMID 35582384, 2021).
tumor (continued). "In addition, IHC staining of mouse tumour tissues showed that the protein expression of PCNA, Bcl2, vimentin, p-PI3K, and p-AKT was reduced, which was consistent with the results of the in vitro studies." (PMID 33995637, 2021). "Meanwhile, a reduced proportion of areas with PCNA-positive cells was observed in treated tumor." (PMID 33986437, 2021). "Downregulation of FBXO43 inhibits the BC tumor growth by limiting its interaction with PCNA." (PMID 34645483, 2021). "Furthermore, we examined the effects of klotho on cell proliferation in tumor tissues derived from control and klotho overexpressed mice using anti-PCNA or anti-Ki67 antibody." (PMID 32614356, 2020). "Cell proliferation in tumor section was detected by staining with anti-PCNA monoclonal antibody." (PMID 33014855, 2020). "There was no clear association between IGF1R/PCNA colocalization and tumor proliferation as determined by mitotic count (data not shown)." (PMID 32701997, 2020). "GLP administration (25 and 100 mg/kg) significantly inhibited tumor growth, as evidenced by the decreased tumor volume and tumor weight, as well as histological features of tumor tissues with concomitant down-regulation of proliferating cell nuclear antigen (PCNA) proliferative marker." (PMID 32530032, 2020). "Therefore, we next investigated the expressions of PCNA and Ki67 as tumor cell proliferative markers in the liver tissues." (PMID 32121064, 2020). "Besides, the Ki‐67 and PCNA IHC staining of the dissected tumour tissues were also distinctly reduced in the co‐treatment group." (PMID 33047871, 2020). "We analyzed the mRNA level of tumor-associated genes such as Cadherin-1, Ki-67, PCNA, β-catenin, STAT3, and COX2, as well as the protein levels of tumor marker VEGF, its downstream transcription activator STAT3 and p-STAT3, and the tumor proliferation marker PCNA." (PMID 32582527, 2020). "Necrosis of tumor cells, infiltration of inflammatory cells, and fibrous tissue proliferation were promoted, and the expression of the proliferating cell nuclear antigen (PCNA) and vascular endothelial growth factor (VEGF) was reduced compared with the control group." (PMID 33163082, 2020). "In addition, it showed that tumours from histamine-treated mice presented a reduced mitotic index and a lower percentage of PCNA-positive cells." (PMID 31748740, 2020). "Finally, tumor tissues were deeply immunostained for Ki67 and PCNA, which are indicative of the proliferative capacity of the cells and suggests strong cell division." (PMID 31927530, 2020). "Accordingly, the quantification of PCNA-positive cells in the corresponding slides indicated that tumor proliferation was strongly diminished by regorafenib/A-1331852 co-administration (100 ± 88), compared to regorafenib- or vehicle-treated mice (869 ± 320 and 1573 ± 395, respectively)." (PMID 32024199, 2020). "In addition, we found that there was a significant positive correlation between the PGAM1 and advanced TNM stage and tumor proliferation marker (Ki-67 and PCNA) expression levels." (PMID 32855383, 2020). "By constructing a monoclonal antibody against PCNA, the Porgador group was able to demonstrate that blocking this tumor antigen unleashes NK cell activity in-vitro and in-vivo, and promotes tumor clearance in murine xenograft models of autologous HNSCC patient NK cells." (PMID 32153582, 2020). "Finally, down-modulation of NK cell activity can also be mediated by inhibitory signals triggered by the engagement of NKp44 receptor with its ligand proliferating nuclear cell antigen (PCNA) expressed in different tumor types." (PMID 32218226, 2020). "These might suggest an active DNA replication of cBM-MSCs, especially for proliferating cell nuclear antigen (PCNA) which is used as an indicator of proliferative activity of neoplasm and osteoblast." (PMID 33244029, 2020). "Subsequently, tumor tissue sections were prepared and stained with H & E and PCNA." (PMID 31823522, 2020).
tumor (continued). "Moreover, MEG3 strongly decreased tumor growth and volume, and the expression of proliferating cell nuclear antigen (PCNA) and Ki67." (PMID 33109195, 2020). "In addition, the abundance of an array of tumor markers, such as PCNA, Ki-67, MMP9, E-cadherin, and N-cardherin were quantified." (PMID 33928018, 2020). "Furthermore, tumor tissues were stained by immunohistochemistry assay with Ki67 and PCNA (Proliferating Cell Nuclear Antigen), which are markers of cell proliferation, and showed lower expression in OSW‐1‐treated xenografts compared with control group." (PMID 32515123, 2020). "In addition, the expression of TUNEL-positive cells was significantly amplified, while the expression of PCNA-positive cells was dramatically reduced in the tumor tissue with combined treatment of radotinib and Ara-C." (PMID 33276759, 2020). "Besides, hsa_circ_0005785 expression by qRT-PCR analysis, HE staining, and the expression of PCNA by immunohistochemical staining were conducted in the resected tumor tissues." (PMID 32974140, 2020). "Tumour proliferation and apoptosis were examined by PCNA, TUNEL and cleaved caspase-3 staining." (PMID 31854220, 2020). "We believe that the IGF1R/PCNA interaction is a basic cellular mechanism to increase DNA stress tolerance during proliferation, but that this mechanism is lost with tumor progression in conjunction with accumulated DNA damage and aberrant strategies to tolerate genomic instability." (PMID 32701997, 2020). "The PCNA protein was sharply upregulated in tumor tissues as well." (PMID 31927530, 2020). "In the xenograft model, the CAt extract suppressed HCC tumor cell growth and prolonged lifespan by inhibiting PCNA protein expression, repressing part of the VEGF-induced autocrine pathway, and triggering strong expression of cleaved caspase-3, which contributed to cell apoptosis." (PMID 33050385, 2020). "Interestingly, in our cohort, the expression of FAK, EZH2, H3K27me3, and PCNA inversely correlated with tumor size: Higher expression of these proteins was found in smaller cirrhotic HCCs." (PMID 32806748, 2020). "Morphometric analysis followed by calculations of the morphological parameters of the tumour tissue showed that in the control group, the numerical density of mitosis was 5.6 ± 0.4 per test area and the volume density of PCNA-positive tumour cells was 62.7 ± 3.8%." (PMID 33147876, 2020). "Moreover, P4HA2 expression was positively related to the expression of Ki67 and PCNA, two neoplasm proliferation markers." (PMID 32226497, 2020). "In addition, tumor sections in the BA-5-treated group had lower expression the proliferative biomarkers Ki-67 and PCNA than those in the control group." (PMID 32575795, 2020). "PCNA, as the cell proliferation status evaluation index, is uniquely expressed in normal proliferative cells and tumor cells and could facilitate tumourigenesis and proliferation of a variety of tumors, including OS." (PMID 31552187, 2019). "And, the pre-targeting group had significantly reduced microvessel density in the tumor tissue around the coagulation necrosis area and had the lowest expression of PCNA in the tumor cells, suggesting that the proliferation of tumor cells is effectively inhibited." (PMID 31061456, 2019).
tumor (continued). "In vivo studies also note that IGF2 tissue expression in CRC correlates with expression of other proliferation markers, e.g., proliferating cell nuclear antigen (PCNA), which confirms the role of this growth factor in tumor cell proliferation through a paracrine mechanism." (PMID 31623387, 2019). "Moreover, tumor tissues with high CD73 expression also exhibited high proliferating cell nuclear antigen levels." (PMID 30971294, 2019). "Thus, while a clear decrease in tumor numbers, size and histology was apparent after 5 weeks of Rapamycin treatment, the remnant tumor foci were PCNA staining even in the Rapamycin-treated group." (PMID 30863496, 2019). "In addition, the results of immunohistochemistry showed that AIM2, as well as the cell proliferation marker Proliferating Cell Nuclear Antigen (PCNA) in tumor tissues were significantly downregulated by luteolin." (PMID 30833546, 2019). "In addition, the tumours from the 9a-treated mice showed lower nuclear levels of immunostaining for Ki-67 and PCNA than those of the control mice, which was suggestive of inhibited proliferation in the SR tumours." (PMID 31754201, 2019). "Interestingly, PCNA staining revealed that there was a significant decrease in proliferation in the tumours exposed to GA relative to the controls, consistent with the lower mitotic index in the HE stained tissue." (PMID 31578236, 2019). "Moreover, knockdown of CLEC5A downregulated protein level of MMP‐2, MMP‐9, PCNA and Akt phosphorylation in tumour tissues." (PMID 30834619, 2019). "The synergistic effect of N2O-mbs on HIFU treatment was also evaluated by H&E, PCNA, and TUNEL staining, which demonstrated that N2O-mbs combined with HIFU irradiation could cause larger scale of tumor cell necrosis as compared with HIFU–C3F8-mbs group." (PMID 31845016, 2019). "We performed immunohistochemical staining for two markers of cell proliferation, namely, Ki-67 and PCNA, and found that the staining intensities for Ki-67 and PCNA were weaker in the tumor tissues obtained from NPTX2 knockdown cells than in those obtained from shRNA control cells." (PMID 30833544, 2019). "The suppressed LAC phenotype in KrasG12D:Adam17ex/ex mice was associated with a significant reduction in the proliferative index of tumor‐bearing KrasG12D:Adam17ex/ex lungs, as measured by cellular reactivity to proliferating cell nuclear antigen (PCNA), compared to KrasG12D lungs (and EV1D)." (PMID 30833304, 2019). "The lowest PCNA levels in individual samples were found in the tumors with the lowest growth rate (data not shown), indicating a good correlation between the amount of PCNA found and the tumor growth rate calculated for each tumor." (PMID 31275861, 2019). "Terminal deoxynucleotidyl transferase dUTP nick end labeling (TUNEL) staining results, in support of PCNA staining, revealed that both gemcitabine and NK cells treatment led to induction of apoptosis in tumor tissues; with the NK cell-treated group showing the most robust induction of apoptosis." (PMID 31324057, 2019). "Moreover, immunoblotting analysis was performed to detect the levels of the proliferation (PCNA) marker and anti‐apoptosis marker (Bcl‐2) in xenograft tumour tissues." (PMID 31483572, 2019). "On cell membrane, PCNA interrupts the recognition of tumor cells by natural killer cells." (PMID 31600334, 2019). "Therefore, the main aim of this study was to investigate the correlation between the expression of PCNA at the invasive tumour front and the IFG histological grading in OSCCs." (PMID 31672124, 2019). "Finally, double positive tumor cells (CK-19+ and PCNA+) were present in greater numbers in the bone marrow of Lgals3−/− mice, regardless of the expression of Gal-3 in 4T1 cells." (PMID 31949431, 2019). "The expression levels of PCNA supported that tumor cell proliferation was reduced by QE treatment." (PMID 31273958, 2019). "In short, the tumor sections of each group were stained with PCNA and examined under a microscope." (PMID 30770785, 2019).
tumor (continued). "Additionally, the exposure of U251-xenograft nude mice to 2 mg/kg of trifluoperazine further enhanced tumor growth (as observed in Ki67 and PCNA-positive cells), and inhibited apoptosis in the mouse model." (PMID 31231472, 2019). "However, PCNA and Ki‐67 expression were reduced in tumour cell xenografts injected with QKI‐6 overexpressing T24 cells." (PMID 31449345, 2019). "We also found that NEAT1 knockdown reduced the PCNA expression level in xenograft tumour model." (PMID 30407674, 2019). "Given that tumor cells are more active in replication and contain much higher levels of damaged DNA than normal cells, they are more vulnerable to the stress of downregulation or inhibition of PCNA function." (PMID 31600334, 2019). "Furthermore, proliferating cell nuclear antigen (PCNA) and Ki-67 expression as cellular markers for proliferation were ubiquitously higher in tumor tissues with MAP2K4 overexpression compared with those of the control tissues." (PMID 31761784, 2019). "In in vitro diagnostic tests, EPOS/EnVision may be applied to assess progression and malignancy of the tumor in cancer patients through detection of PCNA (proliferating cell nuclear antigen) and Ki-67 antigen in the frozen sections of tissues." (PMID 31342119, 2019). "Furthermore, ectopic expression of QKI‐6 reduced tumour xenograft growth and expression of proliferation markers, Ki67 and PCNA." (PMID 31449345, 2019). "The reduction in tumor size was accompanied by an increase in the expression of cleaved caspase 3 and a decrease in proliferating cell nuclear antigen (PCNA), demonstrating the ability of LG268 to induce apoptosis (cleaved caspase 3) and reduce proliferation (PCNA)." (PMID 31700995, 2019). "However, IHC analysis indicated that the expression of the cell proliferation marker PCNA dramatically decreased in the tumor samples retrieved from the monensin treatment group, compared with that of the control group." (PMID 30559409, 2018). "PCNA expression in IHC staining (cells with nuclear staining were recorded as positive) also has a positive correlation with tumor size, tumor histological type, differentiation grade, nuclear grade, mitotic index, histological grade of malignancy, and lymph node metastasis." (PMID 30373614, 2018). "Moreover, Ki67 and proliferating cell nuclear antigen (PCNA) expression were also lower in tumor tissues compared to that of control group." (PMID 30618730, 2018). "Furthermore, IHC analysis of the proliferative markers Ki67 and PCNA in tumours from each group revealed that there was limited expression of Ki67 and PCNA in the PIM1-deficient tumour tissues, which indicated slower growth compared to the control tissues." (PMID 29472550, 2018). "Then, it was extended that Snail could suppress tumor cell proliferation through binding to flanking region of proliferating cell nuclear antigen (PCNA) gene to decrease its expression." (PMID 30456206, 2018). "Additionally, we observed enhanced tumorigenic potential with a higher number of PCNA positive cells in sections of the tumor resulting from injection of T3M-4-sh-SEMA5A than those injected with T3M-4-Control cells." (PMID 30577767, 2018). "The blots of tumor proliferation biomarker PCNA confirmed BMP5 could affect HT-29 and SW480 cell growth." (PMID 30572883, 2018). "In conclusion, the results revealed that silencing of CD164 could inhibit the proliferation of tumor cells by regulating the expression of proliferation‐related proteins such as Ki67 and PCNA." (PMID 30022623, 2018). "Disruption of intracellular PCNA activity affects tumor cell viability." (PMID 29875773, 2018).